ENSG00000258465 (novel protein)
Gene: Protein-coding gene on chromosome 1 (160,216,800 to 160,285,130, reverse strand). Ensembl gene ENSG00000258465.
Genetic constraint (gnomAD): Loss-of-function variants: 20 observed, 26.07 expected, observed/expected ratio (o/e) 0.77, 90% interval 0.54 to 1.12. Missense variants: 248 observed, 282.39 expected, observed/expected ratio (o/e) 0.88, 90% interval 0.79 to 0.98. Synonymous variants: 79 observed, 96.91 expected, observed/expected ratio (o/e) 0.82, 90% interval 0.68 to 0.98.